EGFR (epidermal growth factor receptor)
Diseases named in the same sentence as EGFR in open-access papers (continued):
Sharing a sentence is not in itself a finding about the gene and the disease.
lung cancer (continued). "Previous studies have reported that epidermal-mesenchymal transition (EMT) is responsible for EGFR-TKI resistance in LUAD and promotes lung cancer metastasis and tumor cell acquisition of stemness." (PMID 36139554, 2022). "Nanogels have been tested for preparations involving cisplatin for lung cancer, and hyaluronic acid nanogels targeting both CD44 and epidermal growth factor receptor (EGFR) for metastatic breast cancer." (PMID 36678717, 2022). "The introduction of epidermal growth factor receptor (EGFR)-tyrosine kinase inhibitors (TKIs) has revolutionized the treatment and significantly improved the overall survival (OS) of lung cancer." (PMID 36139582, 2022). "In lung cancer treatment, KRAS is downstream of the EGFR pathway; therefore, tyrosine kinase-based treatment with gefitinib and erlotinib is ineffective when KRAS is constitutively activated." (PMID 35163506, 2022). "Given that many ncRNAs participate in the modulation of EGFR TKI resistance via multiple signaling pathways, ncRNAs potentially serve as therapeutic targets or agents for EGFR TKI-resistant lung cancer." (PMID 36139582, 2022). "Epidermal growth factor receptor (EGFR) signaling has been shown to positively regulate G9a expression through signal transducer and activator of transcription 3 (STAT3) in EGFR+ lung cancer." (PMID 35740522, 2022). "Further, to explore the mechanisms of COL8A1 promoted lung cancer development, we found COL8A1 activated EGFR via upregulation of IFIT1 and IFIT3." (PMID 35280763, 2022). "Here, we evaluated the expression of NF-κB, AICDA, Akt, IL-6, Jak2, and Stat3 by EGFR-TKI-resistant lung adenocarcinoma (LAC), and found that NF-κB and AICDA are major players in the acquired resistance of lung cancer to TKIs." (PMID 35740609, 2022). "Here, using a non–small cell lung cancer (NSCLC) cell line, we evaluated the EMT-related effects of the epidermal growth factor receptor inhibitor erlotinib alone and in combination with cilengitide, a cyclic RGD-based integrin antagonist." (PMID 35408781, 2022). "Considering the role of these three molecules in lung cancer pathology, the main goal of this study was to assess their serum concentration before and after treatment and investigate how MGP, Gas6, EGFR, and VK1 are modified after one cycle of chemotherapy." (PMID 35053080, 2022). "EGFR is highly expressed in patients with NSCLCs, and the downstream PI3K-AKT signalling activation drives lung cancer angiogenesis, invasion, survival, and metastasis 19-22." (PMID 36185331, 2022). "Genetic alterations of EGFR, MAP2K1, mTOR, TEAD1, and YAP1 in The Cancer Genome Atlas (TCGA) cohorts of lung cancer occurred at respective frequencies of 15.0%, 1.80%, 6.00%, 1.80%, and 2.50%." (PMID 35655775, 2022). "For example, Osimertinib is used for EGFR-driven lung cancers, whereas Dabrafenib with Trametinib is used for BRAF-driven lung cancers." (PMID 35845436, 2022). "A study confirmed that under the action of various small molecule inhibitors against KRAS-, EGFR-, or ALK-driven lung cancer, the intrinsic apoptosis pathway in mitochondria is activated, and activated GSDME mediates apoptosis." (PMID 35311148, 2022). "EGFR palmitoylation has been shown to inhibit EGFR activity and alter downstream signaling in the KRAS mutant lung cancer." (PMID 36619616, 2022). "METTL3 increases the expression of EGFR and TAZ and promotes the growth, survival, and invasion ability of human lung cancer cells; it also plays a role in promoting the translation of lung cancer oncogenes." (PMID 38089085, 2022). "These two EGFR degraders showed effective and selective antitumor activity in EGFR-TKI-resistant lung cancer cells." (PMID 35840984, 2022).
lung cancer (continued). "Aberrant epidermal growth factor receptor (EGFR) activity, one of the most common phenomena in NSCLC, drives the uncontrollable growth of lung cancer cells." (PMID 35494059, 2022). "For example, induction of AREG expression sensitizes lung cancer cells to EGFR TKI and increases the tumorigenic dependence of non-small cell lung cancer on the AREG-induced EGFR signaling pathway, thus enhancing the progression of NSCLC." (PMID 36186485, 2022). "At present, irreversible ErbB family inhibitors against EGFR-TKI resistance, such as afatinib, have achieved good results in large-scale clinical trials and are expected to become part of a new generation of lung cancer targeted therapy drugs." (PMID 35433677, 2022). "Accordingly, several oncogenic genes have been used as biomarkers for lung cancer diagnosis; however, the sensitivities of K-ras-G12C, EGFR, EML4-ALK, and CLIP1-LTK in lung cancer patients are only 14%, 46%, 4%, and 0.5%, respectively." (PMID 35574342, 2022). "EGFR-TKI-resistant lung cancer cells demonstrated that activation of off-target signaling molecules such as SRC, FAK, and YES, conferred resistance to various EGFR-TKIs17,24,25." (PMID 35643725, 2022). "We firstly screened the EGFR and MET signaling, which are the most important pathways in lung cancer progression by Western blot." (PMID 35635086, 2022). "Currently, there are several targeted therapies approved to treat lung cancer, with the targets of interest being ALK, MET, HER2, and EGFR." (PMID 36551663, 2022). "The manufacture of mesoporous silica in combination with anti-EGFR in the form of cetuximab was also carried out to deliver siRNA against polo-like kinase 1 (PLK1), which is critical in lung cancer mitosis." (PMID 36085575, 2022). "Although according to one clinical trial, pembrolizumab did not elicit a significant response in patients with EGFR-mutated lung cancer naïve for EGFR-TKI, even in the presence of high PD-L1 expression, the efficacy of this ICI could be influenced by TME changes during the EGFR-TKI treatment." (PMID 35742933, 2022). "Therefore, it was speculated that Huaier inhibits lung cancer through EGFR." (PMID 35470770, 2022). "In lung cancer, SFK and FAK sustain AKT and MAPK pathway signaling under continuous EGFR inhibition." (PMID 35820889, 2022). "EGFR and RB1, played key roles in cell cycle, functioned in the metastasis and carcinogenesis of head and neck cancer and lung cancer." (PMID 35397555, 2022). "It should be noted that a peculiar affiliation between lung cancer/HER2-positive breast cancer and the interaction between the ER/EGFR pathways has been noted in previous studies." (PMID 35740640, 2022). "Osimertinib, a mutant-specific third-generation epidermal growth factor receptor (EGFR) tyrosine kinase inhibitor (TKI), is emerging as the preferred first-line of treatment for EGFR-mutant lung cancer." (PMID 35943592, 2022). "More targets and mutation sites have been identified, and drugs that are targeting genes such as EGFR and HER2 have been shown to have definite antitumor effects in breast and lung cancers." (PMID 36573110, 2022). "The EGFR signalling-driven ERK and AKT signalling cascades are critical for the development and tumorigenesis of HCC, lung cancer, breast cancer and other cancers." (PMID 36385095, 2022). "For example, a trial of the EGFR inhibitor erlotinib and pan‐FGFR inhibitor dovitinib in metastatic non‐small cell lung cancer was halted early given dose limiting toxicities." (PMID 35224804, 2022). "The epidermal growth factor receptor (EGFR), a major driver of cellular proliferation, differentiation, migration, and angiogenesis, plays an important role in the progression of lung cancer." (PMID 36135023, 2022). "On the other hand, knocking out GSDMD can inhibit the epidermal growth factor receptor (EGFR)/AKT pathway and inhibit the proliferation of lung cancer cells." (PMID 35311148, 2022).
lung cancer (continued). "From January 2012 to October 2019, 3562 patients were diagnosed with lung cancer, and 812 patients with stage IIIB–IV lung adenocarcinoma received EGFR‐TKI as first‐line therapy." (PMID 35394114, 2022). "DUSP3 also dephosphorylates epidermal growth factor receptor (EGFR), suppresses tumor formation by lung cancer cells, and its expression levels are decreased in lung cancer tissues." (PMID 35705979, 2022). "The cultured lung cancer cells were first preincubated with ETTE nanoprobes in PBS, then exposed to EGF to activate the EGFR signaling pathway." (PMID 35105871, 2022). "Therefore, the present study was intended with the aim to identify the interactions of HMs with the target protein “epidermal growth factor receptor (EGFR)” of lung cancer and explore potential drug candidates, which could inhibit the active site of EGFR against HM exposure." (PMID 35607306, 2022). "Anaplastic lymphoma kinase (ALK), epidermal growth factor receptor (EGFR), c-ros Repressor of Silencing 1 (ROS1) as crucial lung cancer gene targets have been unanimously recognized by today academic circles, and the era of targeted therapy has begun." (PMID 35313900, 2022). "To determine the efficacy of osimertinib plus bevacizumab in LM in EGFR-mutant NSCLC, we constructed a model of LM with lateral ventricle injection, and the lung cancer LM xenograft model was confirmed by IVIS imaging, MRI, and H&E." (PMID 35287683, 2022). "The small molecule DNA-PK inhibitor, PI-103 or NU7441, combined with the third-generation epidermal growth factor receptor (EGFR) tyrosine kinase inhibitor (TKI) Osimertinib, led to synergistic effects in TKI-resistant lung cancer cells." (PMID 36499000, 2022). "A simplified and applicable ML model with five most relevant features, KPS, A history of VTE, Recombinant human endostatin, EGFR-TKI, and Platelet count, to predict VTE incidence in lung cancer patients was developed and validated in this study." (PMID 35321110, 2022). "Although many studies have been dedicated to EGFR and VEGF inhibition, there has been a minimal increase reported in the overall survival of lung cancer patients." (PMID 35626731, 2022). "Through the EGFR/AKT signalling pathway, GSDMD increases lung cancer proliferation as well as an unfavorable prognosis." (PMID 36120543, 2022). "EGFR and ALK inhibitors have become the mainstays of treatment in lung cancer therapy, while in recent years a new class of drugs has been able to target the once “un-druggable” KRAS mutation." (PMID 36230484, 2022). "For example, the overexpression of epidermal growth factor receptor (EGFR), which is involved in about 60% of NSCLC tumors and present in about 20% of LUAD tumors, currently has precision medicine implications in treating lung cancer." (PMID 35524179, 2022). "The epidermal growth factor receptor (EGFR), a receptor bound to the cell membrane, has been well-researched during lung cancer development." (PMID 36685487, 2022). "This meta‐analysis aims to clarify the role of the EGFR‐plasma test in prognosis for non‐small cell lung cancer (NSCLC) who have mutant tumors and receive EGFR tyrosine kinase inhibitors (TKIs)." (PMID 34427045, 2022). "In lung cancer cells, METTL3 promotes the translation of EGFR and TAZ, the effector of Hippo pathway." (PMID 36536402, 2022). "To do this, we used gDNA from 293 T cells that harbor the WT EGFR gene, and gDNA from NCI-H1975 [a human lung cancer cell line harboring the T790M (C2369T) and L858R (T2573G) single-nucleotide mutations in the same allele]." (PMID 35664805, 2022). "Moreover, a late stage NSCLC patient had more targeted EGFR-positive exosomes in the blood than early stage patients, thus implying that the number of EGFR-positive exosomes may be correlated with the stage of lung cancer." (PMID 35158999, 2022).
lung cancer (continued). "Sequentially, we evaluated the targetable variations detected ability in different samples, including EGFR, ALK, BRAF V600E, KRAS, MET ex14 skipping, RET, ROS1, ERBB2, which have high evidence in lung cancer." (PMID 36167530, 2022). "After NGS analysis of CTCs from lung cancer patients, more than 50% of patients were found to carry four common mutant genes (Notch1, IGF2, EGFR, and PTCH1)." (PMID 35057806, 2022). "In lung cancer, high expression of AKR1B1 resulted in enhanced glutathione (GSH) synthesis and resistance to EGFR inhibitors in cell lines and xenograft models." (PMID 36463238, 2022). "For lung cancer metastases, ALK-protein and EGF-receptor (EGFR) were analyzed most frequently, with 31 conclusive cases out of 32 analyzed (97%)." (PMID 36605448, 2022). "Anti-EGFR antibody and anti-angiogenesis therapy play an important role in NPC and lung cancer, respectively." (PMID 36138362, 2022). "Consistently, BPL2 significantly reduced the expression of EGFR along with the activation of ERK and AKT, downstream of the EGFR signaling pathway in lung cancer cells." (PMID 36547923, 2022). "As there are many studies regarding EGFR-TKI targeting NSCLC, we verified the drug responsiveness of pelitinib relative to LEPRE1 levels in EGFR-expressing human lung cancer-derived A549 cells." (PMID 35190588, 2022). "The combined DHA and gefitinib treatment suppressed the EGFR signaling in EGFR-mutant human NSCLC PC9 and TKI-resistant A549 lung cancer cells." (PMID 36547898, 2022). "We compared survival in the single lung cancer and LCF groups and analyzed the subgroups in different stages and with different EGFR expression." (PMID 36233811, 2022). "The non-invasive and affordable diagnosis of lung cancer can beaided by salivary mRNA biomarkers (CCNI, EGFR, FGF19, FRS2, and GREB1)." (PMID 37693919, 2022). "Integrin β3 was activated by transforming growth factor-β1 (TGF-β1) to increase the epidermal growth factor receptor (EGFR) tyrosine kinase inhibitor resistance, then EMT and anoikis resistance was observed in lung cancer cell lines." (PMID 36230714, 2022). "Zhou used camrelizumab and apatinib to treat patients with advanced EGFR and ALK wild-type non–small cell lung cancer; he found that the combination regimen significantly reduced reactive capillarity to 15.6%—a rate similar to that in our study." (PMID 35280787, 2022). "Monoclonal antibodies are aimed solely to target receptors such as the Epidermal Growth Factor Receptor, EpCAM receptor, NSE receptor, and other receptors that are abundantly expressed in lung cancer." (PMID 36085575, 2022). "For lung cancer targeted delivery with EGFR overexpression, the surface of these PEGylated SPION nanoparticles has been coated with an anti-EGFR." (PMID 36085575, 2022). "In lung cancer, this is accomplished through IQGAP3's regulation of EGFR-ERK signaling, whereas in hepatocellular carcinoma, this is accomplished by promoting TGF-β, which is a key EMT regulator." (PMID 35355828, 2022). "Among them, Cisplatin, a DNA-targeting Platinum salts, and Erlotinib, a tyrosine kinase inhibitor of EGFR (EGFR-TKI), are frequently used for lung cancer patients." (PMID 35897763, 2022). "The first trials with tyrosine kinase inhibitors targeting EGFR in NSCLC were initiated in 2001, and, since that time, targeted therapies have emerged as an effective management strategy in lung cancer patients." (PMID 35806218, 2022). "ZEB1, TRAF4, and TGF-β1 are involved in lung cancer metastasis by EMT proteins while PD-L1, EGFR, TLR7 and TLR8 are involved in inhibiting the immune system." (PMID 36032679, 2022). "When stratified by PD-L1 levels, even patients with high PD-L1 expression (TPS 50–100%) did not derive as much benefit from chemoIO therapy in EGFR-mutant lung cancers, which is especially disappointing when compared to high PDL1 EGFR-wildtype tumors." (PMID 35884533, 2022).
lung cancer (continued). "Finally, COBAS EGFR mutation test V2 (Roche Molecular Systems, Indianapolis, IN, USA) detects somatic mutations in the EGFR gene from FFPE tumor DNA or plasma ctDNA and is used as a companion diagnostics method for the selection of targeted therapies in lung cancer patients." (PMID 35892331, 2022). "A combination of the epidermal growth factor receptor (EGFR) tyrosine kinase inhibitor (TKI) and anti-VEGF enhanced the anti-tumor efficacy to overcome the EGFR TKI resistance in lung cancer-induced mice." (PMID 36140220, 2022). "To confirm the results produced in lung cancer cells, we repeated some experiments on A431 cell line (squamous cell carcinoma, SCC, cell line), as a model of high EGFR expressing cell line." (PMID 35955669, 2022). "In lung cancer cells, NGI-1 selectively inhibits the proliferation of epidermal growth factor receptor (EGFR)-dependent cell lines by destroying the glycosylation and cell surface localization of EGFR." (PMID 35573732, 2022). "Inhibition of EGFR-STAT/AKT/ERK signalling pathways, a G0/G1 cell cycle arrest and apoptosis in lung cancer cells." (PMID 35813479, 2022). "Moreover, this study suggests that the activation of the mammalian target of rapamycin (mTOR)/CD1 pathway by p38 mitogen-activated protein kinase (MAPK) might be the approach for AR and epidermal growth factor receptor (EGFR) cross-talk, leading to lung cancer development." (PMID 35631448, 2022). "Thus, by engaging a tumor non-autonomous mechanism involving cGAS-STING and innate immunity, the combination of osimertinib and anti-HER3 antibodies could improve the limited therapeutic and stratification options for advanced stage lung cancer patients with mutant EGFR." (PMID 35347108, 2022). "The therapeutic efficiency of curcumin in lung cancer is exhibited by the suppression of COX-2, EGFR, NF-­κB, and PI3K/Akt signaling pathway." (PMID 35399416, 2022). "In lung cancer, especially NSCLC, EMT and bypass signal activation are known mechanisms of resistance after EGFR TKI use." (PMID 35311091, 2022). "The effects of different EGFR-targeted drugs (gefitinib, afatinib, and osimertinib) on NCI-H650 cells and primary lung cancer cells were tested in 2D well plates and 3D lung chips." (PMID 36005014, 2022). "A possible explanation for these differences could involve the geographic or ethnic factors, which has been observed in the enrichment of EGFR mutations in East Asian populations in lung cancer, but not enough evidence is available to support this hypothesis in head and neck cancer." (PMID 35053553, 2022). "It was observed that the mRNA expression of EGFR, MAPK1, Akt1, and SRC were upregulated in the lung cancer tissues whereas the expression of IGF1 and PI3KR1 was reduced as compared to the normal lung tissues." (PMID 36313358, 2022). "We used two strategies, a 2D well plate and a 3D lung chip, to evaluate the effects of different EGFR-targeting drugs (gefitinib, afatinib, and osimertinib) on NCI-H650 cells and primary lung cancer cells." (PMID 36005014, 2022). "Conversely, in stage 1 patients with mutant EGFR, the LCF group had worse survival than the single lung cancer group." (PMID 36233811, 2022). "Along this line, epidermal growth factor receptor (EGFR), a member of the RTK family, is aberrantly activated in various aggressive tumors including glioblastoma multiforme (GBM) and lung cancer." (PMID 35203553, 2022). "Epidermal growth factor receptor (EGFR) and AXL belong to the group of tyrosine kinases, which are overexpressed in lung cancer and their activation promotes tumour development, invasion, and metastasis." (PMID 35171422, 2022). "EGFR and AKT1 have been revealed to play a synergistic tumor-promoting role to aggravate tumor progression in human lung cancer." (PMID 35873484, 2022). "The results showed that SHC1 or EGFR overexpressed in A549 and NCI–H446 lung cancer cells significantly increased proliferation and invasion capacity compared with the control group." (PMID 35706930, 2022).